PIAS4 (protein inhibitor of activated STAT 4)
Diseases named in the same sentence as PIAS4 in open-access papers:
PIAS4 is named in the same sentence as 32 diseases in open-access papers, as found by Europe PMC text mining. Sharing a sentence is not in itself a finding about the gene and the disease. The quoted sentences say what the papers report.
breast carcinoma (9 papers, 2010 to 2026). "We also found that PIAS3 played a deleterious prognostic factor in colorectal cancer (OS, DSS, DFS), while PIAS4 was a risk factor for breast cancer (DFS, RFS), lung cancer (OS) and brain cancer (OS)." (PMID 38528630, 2024). "Enhancement of AMPK activity towards mTORC1 and associated cytostatic effects in MDA-MB-231 breast cancer cells following PIAS4 depletion indicate that inhibition of AMPKα1 SUMOylation could provide a specific way to inhibit cancers with hyperactive mTORC1 signalling." (PMID 26616021, 2015). "Protein inhibitor of activated STAT 4 (PIASy), overexpressed in breast cancer cells, selectively promotes the conjugation of HDAC1 to SUMO2." (PMID 39127633, 2024). "MiR-210 regulates the JAK-STAT signal transduction pathway by targeting PIAS4, thus exerting an effect on breast cancer chemosensitivity." (PMID 34423038, 2021). "PIAS4 depletion reduced growth of breast cancer cells, specifically when combined with direct AMPK activator A769662, suggesting that inhibiting AMPKα1 SUMOylation can be explored to modulate AMPK activation and thereby suppress cancer cell growth." (PMID 26616021, 2015). "However, in breast cancer cell lines, where PIAS4 is overexpressed, it has been observed that PIAS4 preferentially binds SUMO2 to HDAC1, protecting it from ubiquitination and degradation, and promoting its expression and activity that is involved in cancer progression." (PMID 35887358, 2022). "Therefore, miR-210 regulates that breast cancer cell MCF-7 chemotherapy resistance may be accomplished by targeting PIAS4 to regulate the JAK-STAT signal transduction pathway." (PMID 34423038, 2021). "PIAS family members were differentially expressed in breast cancer, as PIAe S2 and PIAS3 were downregulated, whereas PIAS4 has a contradictory trend." (PMID 38590645, 2024). "By targeting PIAS4, it modulates the JAK-STAT signal transduction pathway and affects the sensitivity of breast cancer chemotherapy." (PMID 34423038, 2021).
hepatocellular carcinoma (4 papers, 2016 to 2024). A malignant tumor that arises from hepatocytes. "Indeed, exposure to high glucose (35mM) led to a decrease in SIRT1 expression while simultaneously stimulating PIAS4 expression in both primary mouse hepatocytes and immortalized hepatocellular carcinoma cells (HepG2)." (PMID 27285989, 2016).
liver fibrosis (4 papers, 2016 to 2022). "In an experimental model of liver fibrosis, PIAS4 silencing blocked recruitment of SMAD3, decreasing pro-fibrotic gene expression and ameliorating hepatic fibrosis." (PMID 35066606, 2022). "Researchers found that PIAS4 silencing using short hairpin RNA (shRNA) reduced high-fat high-carbohydrate (HFHC) diet induced liver fibrosis in mice." (PMID 29862292, 2018). "Here we report that PIAS4 mediates SIRT1 repression in cultured HSCs exposed to high glucose and in a mouse model of NASH-associated liver fibrosis." (PMID 27323886, 2016). "Here we report that transcriptional repression of SIRT1 by PIAS4 contributes to liver fibrosis in response to excessive glucose." (PMID 27323886, 2016). "Lentivirus-mediated delivery of short hairpin RNA (shRNA) targeting PIAS4 in mice ameliorated MCD diet induced liver fibrosis by normalizing SIRT1 expression in vivo." (PMID 27323886, 2016). "In order to resolve this issue and assign a more precise, cell-autonomous role of PIAS4 in liver fibrosis, future study should take advantage of the Cre-Flox system to specifically delete PIAS4 in different hepatic cells." (PMID 27323886, 2016). "We show here that lentivirus mediated PIAS4 knockdown in MCD-fed mice alleviates liver fibrosis, which could be explained by PIAS4 mediated SIRT1 trans-repression in HSCs." (PMID 27323886, 2016). "Since there was a decrease in inflammatory infiltrates and a parallel decrease in pro-inflammatory mediators in the liver following PIAS4 depletion, an equally plausible explanation could be that down-regulation of liver fibrosis might be secondary to inhibition of liver inflammation." (PMID 27323886, 2016). "Thus, we concluded that PIAS4 might contribute to liver fibrosis by modulating SIRT1-depenent SMAD3 acetylation." (PMID 27323886, 2016). "Therefore, targeting PIAS4 might facilitate the development of novel therapeutic solutions against liver fibrosis in the context of NASH." (PMID 27323886, 2016). "Taken together, our data suggest SIRT1 trans-repression by PIAS4 plays an important role in HSC activation and liver fibrosis." (PMID 27323886, 2016). "PIAS4 promotes HSC activation and liver fibrosis by stimulating SMAD3 acetylation and target binding in a SIRT1-dependent manner." (PMID 27323886, 2016).
lung carcinoma (3 papers, 2019 to 2024). "On the one hand, it has been observed that hypoxia-induced PIAS4-mediated sumoylation of the migration regulator SLUG increases its repressor capacity, decreasing the expression of target genes such as CDH1, promoting migration, invasion and metastasis in lung cancer." (PMID 35887358, 2022).
viral infection (3 papers, 2016 to 2024). "The efficacy of PIAS4 and PIAS1 function as intrinsic antiviral factor towards intracellular viral infection was investigated." (PMID 38590645, 2024). "Moreover, this research complements the recent identification of PIAS4 as an intrinsic antiviral factor, supporting a role for PIAS proteins as both positive and negative regulators of host immunity to virus infection." (PMID 27099310, 2016).
atherosclerosis (1 paper, 2012). A disease characterized by the build-up of fatty material and calcium deposition in the arterial wall resulting in partial or complete occlusion of the arterial lumen.
cystic fibrosis (1 paper, 2021). Autosomal recessive disorder caused by pathogenic variants in the CFTR gene (cystic fibrosis transmembrane conductance regulator), which encodes a chloride and bicarbonate channel expressed in epithelial cells, and follow the diagnosis criteria. "In cystic fibrosis bronchial epithelial (CFBE) airway cells, where all experiments were performed, our prior study demonstrated that PIAS4 overexpression increased the expression of both WT and F508del CFTR; for both proteins, its impact was greatest on the immature form, band B CFTR." (PMID 34764878, 2021).
gastric cancer (1 paper, 2024). A primary or metastatic malignant neoplasm involving the stomach. "Reduction in KDM5B ubiquitination mediated by PIAS4 promotes adaptation of gastric cancer cells to hypoxia." (PMID 38842683, 2024).
HCMV infection (1 paper, 2024). "WT HCMV infection also substantially increased the accumulation of PIAS-type E3-SUMO ligases, including PIAS1, PIAS3, and PIAS4, as well as PIAS2, albeit to a much lesser extent." (PMID 38768227, 2024).
pancreatic cancer (1 paper, 2021). "PIAS4 has been identified as a hypoxia signaling activator in pancreatic cancer cells." (PMID 34277436, 2021).
pulmonary fibrosis (1 paper, 2025). Chronic progressive interstitial lung disorder characterized by the replacement of the lung tissue by connective tissue, leading to progressive dyspnea, respiratory failure, or right heart failure. "The FIEL1 inhibitor BC-1485, which also binds to the substrate PIAS4 in the HECT domain region, shows potent antifibrotic properties by stabilizing PIAS4 and suppressing TGF-β signaling in both murine models of pulmonary fibrosis and human MRC5 cells." (PMID 40901482, 2025).
steatosis (1 paper, 2016). Increased lipid within the cytoplasm of cells. "Therefore, PIAS4 might play a critical role in promoting steatosis-associated fibrogenesis in vivo likely through repressing SIRT1 transcription." (PMID 27323886, 2016).
cancer (13 papers, 2010 to 2026). A tumor composed of atypical neoplastic, often pleomorphic cells that invade other tissues. "In this study, we analyzed the expression of PIAS family genes (PIAS1, PIAS2, PIAS3, and PIAS4) in 33 different types of cancer." (PMID 38528630, 2024). "PIAS4 is closely related to the occurrence and progression of certain types of human cancers (such as pancreatic cancer and liver cancer)." (PMID 38528630, 2024). "We also found that PIAS4 was also significantly down-regulated in two cancer types and up-regulated in fifteen cancer types." (PMID 38528630, 2024). "In renal cell carcinoma, pVHL oligomerization by PIAS4-mediated SUMOylation enhances HIF-1α stabilization to promote cancer cell migration, clonogenicity, and migration." (PMID 33273928, 2020). "Previously, our laboratory has identified a SUMOylation dependent pathway wherein the SUMO E3 ligase PIASy (PIAS4) represses SIRT1 expression in response to hypoxia in cancer cells." (PMID 27285989, 2016). "Previous studies have shown that PIAS4 can be activated by hypoxia, which is a critical factor in regulating energy metabolism, in cancer cells." (PMID 27285989, 2016). "PIAS4 is involved in the sumoylation of HDAC1, an essential epigenetic regulator belonging to a conserved family of deacetylases that may be implicated in cancer progression." (PMID 35887358, 2022). "However, contrary to PIAS1 and PIAS3, PIAS4 favors the survival of cancer cells, promoting the overexpression and stability of lysine demethylase 5B (KDM5B) in hypoxia through its sumoylation, thus provoking the inhibition of CDKN1A (P21) transcription." (PMID 35887358, 2022). "Finally, for DMRs whose associated genes had increased expression upon treatment with FQI1, we observed enrichment of GO terms for pathways in cancer (e.g. PIAS4, SMAD3, TRAF4, MAP2K1) and RNA transport (e.g. NUP188, EIF3A, NUP35, RAN) in both hyper and hypomethylated DMRs." (PMID 27845898, 2016). "In hypoxic conditions, the levels of SUMOylation proteins sharply increase in cancer cells, including SUMO-1, the SUMO E3 ligase PIAS4, the SUMO enhancer RSUME, and SENP1." (PMID 33273928, 2020). "In contrast, PIAS4, a regulator with extensive CNV deletions, showed significantly lower expression in cancer tissues." (PMID 33123273, 2020). "Based on this finding, we might hypothesize that ZNF143’s potential to change the main cancer signaling pathways may originate from CDKN1B, PIAS4, CTBP2, and ABCC1." (PMID 36675976, 2022). "Here, CDKN1B, PIAS4, CTBP2, and ABCC1 could be the potential source for ZNF143 to alter the major cancer signaling pathways." (PMID 36675976, 2022). "Based on this result, we could conclude that CDKN1B, PIAS4, CTBP2, and ABCC1 could be the potential source for ZNF143 (because these genes link more biological functions) to alter the major cancer signaling pathways." (PMID 36675976, 2022).
tumor (9 papers, 2010 to 2024). "The tumor-specific component of the ICI resistance was due to genetic loss of IFNGR1/2 and JAK2, and amplification of IFN signaling inhibitors SOCS1 and PIAS4." (PMID 35269844, 2022). "The overall expression of PIAS2 and PIAS4 in tumor should be described more in detail." (PMID 38590645, 2024). "Induction of PIAS4 by hypoxia also causes it to interact with and suppress the tumor suppressor VHL, facilitating its oligomerization, which inhibits its function as a tumor suppressor in HIF1α-dependent and independent manners, contributing to overall tumor progression." (PMID 35887358, 2022). "The fixed nature of the PIAS4 and NUMB lesions supports a model suggesting that these likely promoted the BRCA2 phenotype of this tumor." (PMID 34011996, 2021). "In addition, PIAS4 also mediates the regulation of AMPK, involved in the inhibition of several cellular processes that are important for tumor progression." (PMID 35887358, 2022).
infection (6 papers, 2015 to 2025). The state of being infected such as from the introduction of a foreign agent such as serum, vaccine, antigenic substance or organism. "We report that PIAS4 localized to sites associated with viral DNA throughout infection." (PMID 26937035, 2016). "The increase in PIAS4 protein expression during infection is most likely achieved through changes in its translational or posttranslational regulation." (PMID 26937035, 2016). "Mouse PIAS4 binds the capsid protein of Moloney murine leukemia virus and mediates its SUMOylation to promote the formation of circular viral DNAs or integrated provirus during early stages of infection." (PMID 41413919, 2025). "The results showed that C protein is able to bind to PIAS4 in MDBK cell upon infection with BVDV." (PMID 32321515, 2020). "While the SAP domain regulates MAR association, the LxxLL sequence, PINIT domain, SIM, or carboxyl (C)-terminal acidic domain (AD) may mediate important protein-protein interactions that regulate PIAS4 localization during infection." (PMID 26937035, 2016). "We show that PIAS4 relocalizes to nuclear domains that contain viral DNA throughout infection." (PMID 26937035, 2016). "Taken together, our data demonstrate that PIAS1 and PIAS4 independently contribute toward the intrinsic antiviral immune response to HSV-1 infection as part of a coordinated host response to infection that is ultimately counteracted by the E3 ubiquitin ligase activity of ICP0." (PMID 27099310, 2016). "Multiple mechanisms to recruit PIAS4 into replication compartments may represent a cellular antiviral “failsafe” or could indicate that PIAS4 has multiple roles during infection." (PMID 26937035, 2016). "Downregulation of mir-29 or let-7 during infection provides one means whereby PIAS4 translation could be altered to increase protein expression (73, 86, –, 88)." (PMID 26937035, 2016). "The accumulation of endogenous PIAS4 in HSV-1 replication compartments increased in prominence as infection progressed, which could result from accumulation of PIAS4, an increase in PIAS4 protein expression, or both." (PMID 26937035, 2016). "As infection progressed, endogenous PIAS4 protein levels increased." (PMID 26937035, 2016). "While both proteins localize to nuclear domains that contain viral DNA throughout infection, PIAS1 is more prominently recruited to domains that contain infecting HSV-1 genomes, while PIAS4 is more prominently recruited into replication compartments." (PMID 27099310, 2016). "During infection with ICP0-null mutant HSV-1, PIAS1 localized to replication compartments, although this localization phenotype was less prominent than that of PIAS4." (PMID 27099310, 2016). "This increase was most prominent during wild-type infection, demonstrating that PIAS4 is not a target for ICP0-mediated degradation." (PMID 26937035, 2016). "The differential colocalization of PIAS4 with PML in cells that have been infected or not indicates that PIAS4 localization is differentially regulated during infection." (PMID 26937035, 2016). "During infection with ICP0-null mutant HSV-1, PIAS4 SIM-mediated direct or indirect interactions with PML predominate, suggesting that infection enhances PIAS4 SIM-mediated interactions over those mediated by its other domains." (PMID 26937035, 2016). "As PIAS4 localizes to domains that contain HSV-1 genomes throughout infection, whether or not PIAS1 also accumulates in replication compartments was evaluated." (PMID 27099310, 2016). "However, how PIAS4 catalytic activity is regulated, or if PIAS4 even mediates SUMOylation events during infection, is not yet known." (PMID 26937035, 2016). "Moreover, PIAS4 also directly binds to and represses IRF3, which could provide an added level of IRF3 suppression during infection." (PMID 26937035, 2016).
infection (continued). "The almost full depletion (by 80 to 90%) of free SUMO following the overexpression of eYFP.PIAS4 or inhibition of the proteasome is in stark contrast to the levels of depletion during HSV-1 infection (20 to 30%) and supports the concept that free SUMO pools are regulated during infection." (PMID 26937035, 2016).
PIAS4 also shares sentences with these, for which no sentence is quoted: colorectal cancer (2 papers); schizophrenia (2); Arrhythmia (1); autism (1); brain cancer (1); diabetes (1); Flavivirus Infections (1); glomerulonephritis (1); heart failure (1); Hepatic steatosis (1); Hyperinsulinemia (1); inflammation (1); inflammatory bowel disease (1); lung adenocarcinoma (1); neurological disorders (1); synovial sarcoma (1); type 2 diabetes (1).